SLC25A22 (solute carrier family 25 member 22)
Description:
Mitochondrial glutamate/H(+) symporter. Responsible for the transport of glutamate from the cytosol into the mitochondrial matrix with the concomitant import of a proton. Plays a role in the control of glucose-stimulated insulin secretion (By similarity).
Synonyms: GC-1; GC1; FLJ13044; NET44; EIEE3; DEE3
Tractability: Antibody: UniProt predicts a signal peptide or a membrane-spanning region. PROTAC: ubiquitination databases record sites on it; its protein half-life has been measured.
Gene: Protein-coding gene on chromosome 11 (790,474 to 798,316, reverse strand). Ensembl gene ENSG00000177542.
Subcellular location: Mitochondrion inner membrane
Subcellular location (Human Protein Atlas): Mitochondria; Nucleoplasm
Pathways (Reactome):
Metabolism: Malate-aspartate shuttle
Transport of small molecules: SLC-mediated transport of neurotransmitters
Gene Ontology:
Molecular function: amino acid:proton symporter activity; L-glutamate transmembrane transporter activity; L-aspartate transmembrane transporter activity
Biological process: L-glutamate transmembrane transport; aspartate transmembrane transport; malate-aspartate shuttle; neurotransmitter transport; regulation of insulin secretion; L-aspartate transmembrane transport; proton transmembrane transport; transmembrane transport
Cellular component: mitochondrial inner membrane; mitochondrion
Genetic constraint (gnomAD): Loss-of-function variants: 25 observed, 34.42 expected, observed/expected ratio (o/e) 0.73, 90% interval 0.53 to 1.01. The synonymous counts are far from expectation, so gnomAD's model fits this gene poorly and the ratio says little. Missense variants: 390 observed, 427.08 expected, observed/expected ratio (o/e) 0.91, 90% interval 0.84 to 0.99. Synonymous variants: 245 observed, 193.61 expected, observed/expected ratio (o/e) 1.27, 90% interval 1.14 to 1.41.
Gene-disease validity (ClinGen):
ClinGen rates the evidence that SLC25A22 causes each of these diseases.
genetic developmental and epileptic encephalopathy (autosomal recessive): Definitive. A complex neurodevelopmental disorder characterized by a range of developmental delays and epileptic encephalopathy phenotypes.
Homologues: Orthologues: chimpanzee SLC25A22 (99% identical), mouse Slc25a22 (96% identical), rat Slc25a22 (95% identical), pig SLC25A22 (94% identical), guinea pig SLC25A22 (93% identical), dog SLC25A22 (92% identical), tropical clawed frog slc25a22l (80% identical), macaque SLC25A22 (74% identical). Paralogues in human: SLC25A18 (63% identical), SLC25A12 (32% identical), SLC25A13 (32% identical), SLC25A21 (27% identical), SLC25A39 (27% identical), SLC25A1 (26% identical), SLC25A10 (26% identical), SLC25A20 (26% identical), SLC25A48 (26% identical), UCP3 (25% identical), SLC25A26 (25% identical), SLC25A11 (25% identical), and 37 more.
Diseases named in the same sentence as SLC25A22 in open-access papers:
SLC25A22 is named in the same sentence as 37 diseases in open-access papers, as found by Europe PMC text mining. Sharing a sentence is not in itself a finding about the gene and the disease. The quoted sentences say what the papers report.
colorectal cancer (9 papers, 2017 to 2025). A primary or metastatic malignant neoplasm that affects the colon or rectum. "SLC25A22, which encodes the mitochondrial glutamate transporter, is overexpressed in colorectal cancer (CRC) and is essential for the proliferation of CRC cells harboring KRAS mutations." (PMID 29254168, 2017). "SLC25A22 exerts oncogenic effects in colorectal cancer, gallbladder cancer, and osteosarcoma cells, mainly through its transport of glutamate across the inner mitochondrial membrane to the mitochondrial matrix." (PMID 37051693, 2023). "Previous studies have shown that the knockdown of SLC25A22 reduces ATP production through the TCA cycle in colorectal cancer cells." (PMID 37051693, 2023). "In contrast to SLC5A8, SLC25A22 reportedly plays a tumor-promoter role in colorectal cancer." (PMID 38366023, 2024). "In addition, SLC25A22 promoted the development and metastasis of colon cancer in mice, and colorectal cancer patients overexpressing SLC25A22 have a shorter survival time than patients with low SLC25A22 expression." (PMID 38366023, 2024). "For example, SLC25A22, a glutamate carrier that facilitates the transport of glutamate across the IMM into the mitochondria matrix, promotes cell proliferation and tumor progression of colorectal cancer with KRAS mutations via intracellular synthesis of aspartate." (PMID 34568013, 2021). "A recent study showed that the knockdown of SLC25A22 suppressed aspartate synthesis and reduced NADPH production via the tricarboxylic acid (TCA) cycle in colorectal cancer cells." (PMID 37051693, 2023).
epilepsy (6 papers, 2017 to 2025). A brain disorder characterized by episodes of abnormally increased neuronal discharge resulting in transient episodes of sensory or motor neurological dysfunction, or psychic dysfunction. "Colleaux, Molinari, Salih, Walsh and colleagues identified SLC25A22 as being linked to epilepsy of infancy." (PMID 40539845, 2025). "We found 39 candidate genes and investigated these genes through in situ hybridization and loss-of-function studies, identifying SLC25A22, encoding a mitochondrial glutamate carrier, as a potential epilepsy gene." (PMID 40539845, 2025). "This may account for, at least in part, poorly understood mechanisms underlying epilepsy associated with SLC25A22 variants." (PMID 40539845, 2025). "Out of the 14 patients carrying 22q13 deletions and having seizures, 4 were carrying an additional CNV covering a known risk gene for epilepsy: KCNT1 (OMIM: 608167), MYT1L (OMIM: 613084), DEAF1 (OMIM: 602635) and SLC25A22 (OMIM: 609302)." (PMID 29263841, 2017). "SLC25A22 deficiency has been considered to cause an early-onset seizure disorder with no associated biochemical abnormalities." (PMID 28255779, 2017). "Therefore, SLC25A22 deficiency patients present phenotypes spanning from very severe cases, with intractable epilepsy, no motor acquisition, vegetative state and early death, to moderate cases with tractable epilepsy, some motor acquisition, no microcephaly or suppression bursts." (PMID 32340404, 2020).
Epileptic encephalopathy (4 papers, 2019 to 2025). A condition in which epileptiform abnormalities are believed to contribute to the progressive disturbance in cerebral function. "Biallelic loss of function variants in SLC25A22 result in severe early onset malignant partial migrating seizures of infancy and early epileptic encephalopathy." (PMID 33426505, 2020).
gallbladder cancer (4 papers, 2019 to 2023). "Slc25a22 mRNA and protein expression are significantly upregulated in tumor tissues and cell lines of gallbladder cancer, and downregulation of Slc25a22 suppresses tumor cell migration and proliferation and promotes apoptosis." (PMID 36619916, 2022). "Our results demonstrated there was high expression of SLC25A22 in gallbladder cancer and that it played a key role it played tumor progression including in vitro and in vivo." (PMID 30814911, 2019).
colon cancer (3 papers, 2022 to 2025). "In KRAS-mutated colon cancer cells, SLC25A22-mediated Gln breakdown reduces H3K4me3 methylation, stimulates the activation of the Wnt/beta-catenin signaling pathway, and diminishes the sensitivity of colon cancer cells to chemotherapeutic agents." (PMID 40276500, 2025). "In KRAS mutant colon cancer cells, SLC25A22 promotes the accumulation of succinic acid, a metabolite of glutamine in the tricarboxylic acid cycle, which further increases the local methylation degree of DNA and then promotes the activation of Wnt signaling pathway." (PMID 35734400, 2022).
osteosarcoma (3 papers, 2022 to 2023). A usually aggressive malignant bone-forming mesenchymal neoplasm, predominantly affecting adolescents and young adults. "The mitochondrial transporter SLC25A22 is highly increased in osteosarcoma and is associated with a poor prognosis in osteosarcoma patients." (PMID 35518353, 2022). "In osteosarcoma, overexpression of SLC25A22 increased osteosarcoma cells proliferation, invasion, and migration in vitro, as well as tumour growth and lung metastasis of in vivo xenograft models." (PMID 36672360, 2023).
CNS cancer (2 papers, 2020 to 2023). "There were one, five and four studies showing a statistically significant increase in the mRNA expression level of TUBB6, RAB5, and SLC25A22 in brain and CNS cancer tissues, in comparison with normal tissues." (PMID 33193654, 2020). "aimed to determine whether mitochondrial function is affected by the absence of SLC25A22 during glioma cell invasion." (PMID 38253025, 2023).
developmental delay (2 papers, 2017 to 2025). "In patients with SLC25A22 variants, seizures typically occurred early in life, and, in severe cases, developmental delays were observed." (PMID 40539845, 2025). "In conclusion, mutations in SLC25A22 cause developmental delay with late-onset seizures as well as neonatal-onset seizures." (PMID 28255779, 2017).
infantile epileptic encephalopathy (2 papers, 2018 to 2021). an epileptic condition characterized by epileptiform abnormalities associated with progressive cerebral dysfunction. "Mutations in the Slc25a22 gene are associated with early infantile epileptic encephalopathy and more than 800 glutamic acid related disorders such as major depression, bipolar disorder, psychosis, and motor neuron disease." (PMID 30537945, 2018).
pancreatic ductal adenocarcinoma (2 papers, 2023 to 2025). An infiltrating adenocarcinoma that arises from the epithelial cells of the pancreas. "Solute carrier family 25 member A22 (SLC25A22) is a glutamate transporter in the inner mitochondrial membrane that is known to suppress ferroptosis in pancreatic ductal adenocarcinoma (PDAC)." (PMID 40298644, 2025). "Here, we identify solute carrier family 25 member 22 (SLC25A22), a mitochondrial glutamate transporter, as a driver of ferroptosis resistance in pancreatic ductal adenocarcinoma (PDAC) cells." (PMID 37051693, 2023).
colorectal tumor (1 paper, 2017). "Thus, our studies demonstrated that SLC25A22 is an essential regulator of the metabolic system of KRAS-mutant colorectal tumor and its overexpression promotes tumor cell growth, which could provide more insights into KRAS-mutant CRC therapy with treatment of polyamine-inhibitor." (PMID 29254168, 2017).
Graves disease (1 paper, 2024). Graves' disease is an autoimmune disorder that leads to overactivity of the thyroid gland (hyperthyroidism).It is caused by an abnormal immune system response that causes the thyroid gland to produce too much thyroid hormones. "The analysis identified several mitochondrial proteins downregulated by HFD, including the citrate carrier (SLC25A1), the dicarboxylate acid carrier (SLC25A10), a glutamate carrier (SLC25A22), and a carrier associated with Graves’ disease (SLC25A16)." (PMID 39111307, 2024).
hippocampal atrophy (1 paper, 2024). "Integrative analysis using neuroimaging data and hippocampal TWAS-predicted gene expression of the three susceptibility genes showed an inverse correlation of SLC25A22 with hippocampal atrophy rate in AD patients, which outweighed the impacts of sex, age, and apolipoprotein E4 (ApoE4)." (PMID 38858380, 2024).
hyperprolinemia (1 paper, 2020). Hyperprolinemia is when there isan excess of a particular protein building block (amino acid), called proline, in the blood. "Moreover, some patients with SLC25A22 deficiency manifest hyperprolinemia, which might be explained by assuming that dysfunctional GC1 activity diminishes or abolishes the export of proline-derived glutamate from mitochondria leading to accumulation of proline in the body." (PMID 32340404, 2020).
liver abscesses (1 paper, 2025). "Subsequently, we measured the mRNA expression of SLC25A22, SLC25A33, and SLC25A37, along with that of pro-inflammatory cytokines, including TNF-α, IL-6, and IL-1β, in CD14+ monocytes from sepsis patients with liver abscesses." (PMID 40384854, 2025).
lung adenocarcinoma (1 paper, 2025). A carcinoma that arises from the lung and is characterized by the presence of malignant glandular epithelial cells. "The purpose of this study was to analyze the effect of SIRT3-mediated deacetylation of mitochondrial SLC25A22 on RAS-selective lethal 3 (RSL3)-induced ferroptosis in lung adenocarcinoma (LUAD)." (PMID 40298644, 2025).
prostate carcinoma (1 paper, 2014). A carcinoma that arises from epithelial cells of the prostate gland. "In the results, two of the four genes (TUBB6, PARM1) are supported by literature for their roles in prostate cancer; nonetheless, the other two (SLC25A22, MYEF2) are less known." (PMID 25151146, 2014).
schizophrenia (1 paper, 2023). A major psychotic disorder characterized by abnormalities in the perception or expression of reality. "Here, we further find that genes contributing to glutamate homeostasis, e.g. the mitochondrial glutamate carrier 1 gene, Slc25a22, as well as the schizophrenia risk gene Grin1, distinctly differentiate between high- and low-performers in mPFC-dependent reversal learning." (PMID 37419882, 2023).
tumor (13 papers, 2017 to 2025). "SLC25A22 glutamate transport function seems crucial for cell proliferation, in vitro migration, and invasion and for tumour metastasis in xenograft models, and it was associated with poor prognosis in patients." (PMID 36672360, 2023). "The different effects of SLC25A22 during RSL3-induced ferroptosis of different tumor cells need further investigation." (PMID 40298644, 2025). "Here, we showed that SLC25A22 knockout synergized with anti-PD1 therapy to mediate tumor regression in KRAS-mutant CRC allograft models, accompanied by synergistic induction of cytotoxic CD8+ T-cell activation." (PMID 37542037, 2023). "Slc25a22 knockout (Slc-KO) CT26 tumors showed lower tumor size together with reduced MDSC (P < 0.01) and PMN-MDSC (P < 0.01), while total T cells and CD8+ T cells were increased (P < 0.01)." (PMID 37542037, 2023). "Single SLC25A22 knockout suppressed tumor growth by ~50% in CT26 and MC38-KrasG12V allografts (P < 0.05)." (PMID 37542037, 2023). "Subsequent analysis of ferroptosis marker prostaglandin-endoperoxide synthase 2, GSH, MDA, and MUFA OA levels confirmed the role of SLC25A22 in inhibiting RSL3-induced ferroptosis in isolated tumor." (PMID 37051693, 2023). "SLC25A22 silencing reduced cell proliferation, migration, and invasion in vitro, as well as tumor and metastasis formation in a xenograft model." (PMID 35008407, 2022). "Consistently, SLC25A22 promoted tumor progression by preventing the process of apoptosis via the mitochondrial pathway." (PMID 30814911, 2019). "In order to further verify the suppressive effect on tumor growth in vivo via downregulation of SLC25A22, we established a stable NOZ cell line with low expression of SLC25A22 by transfecting lentiviral shRNA while shNC was a control." (PMID 30814911, 2019). "The result of IHC staining and qRT-PCR analysis confirmed that SLC25A22 was a tumor-related protein." (PMID 30814911, 2019). "In our experiments, SLC25A22 was shown to be a significant factor in promoting tumor invasion and migration." (PMID 30814911, 2019). "We indicated that the expression of SLC25A22 was significantly upregulated in GBC tumor tissues as well as cell lines." (PMID 30814911, 2019). "In the present study, the result of our experiments indicated that the metastasis and proliferation of the tumor were effectively inhibited by downregulating the expression of SLC25A22." (PMID 30814911, 2019). "We found that the expression of SLC25A22 in tumor tissues was significantly higher than that in adjacent tissues." (PMID 30814911, 2019). "Finally, we demonstrate that siRNA nanoparticles targeting SLC25A22 synergizes with anti-PD1 to suppress tumor growth in KRAS-mutant CRC." (PMID 37542037, 2023). "In immunocompetent male mice and humanized male mice models, SLC25A22 knockout inhibits KRAS-mutant CRC tumor growth with reduced myeloid derived suppressor cells (MDSC) but increased CD8+ T-cells, implying the reversion of mutant KRAS-driven immunosuppression." (PMID 37542037, 2023). "SLC25A22 knockout (SLC-KO) impaired tumor growth (P < 0.001) and tumor weight (P < 0.01)." (PMID 37542037, 2023). "Consistently, SLC25A22 knockout synergized with anti-PD1 to inhibit tumor growth." (PMID 37542037, 2023). "The animal study further confirms that SLC25A22 inhibits ferroptosis-mediated tumor suppression." (PMID 37051693, 2023). "Due to the results of cell apoptosis analysis, SLC25A22 may promote tumor growth by suppressing the mitochondrial apoptosis in GBC." (PMID 30814911, 2019). "In other words, SLC25A22 might promote tumor cell invasion and metastasis via the EMT pathway in GBC." (PMID 30814911, 2019). "This supports the role of SLC25A22 in MDSC recruitment and activation in KRAS-mutant CRC to facilitate tumor growth." (PMID 37542037, 2023). "Taken together, SLC25A22 knockout impaired MDSC infiltration and function, which reinvigorated CD8+ T-cell growth and cytotoxicity, leading to tumor suppression." (PMID 37542037, 2023).
tumor (continued). "In human KRAS-mutant CRC patients, SLC25A22 expression was positively and negatively correlated with MDSC and CD8+ T-cell tumor infiltration, respectively." (PMID 37542037, 2023). "Studies analyzing mutant KRAS CRC found that solute carrier family 25 member 22 (SLC25A22) promoted proliferation and migration of human CRC tumor cells which also resulted in the developments of metastases in CRC xenograft mouse models." (PMID 36090030, 2022). "As SLC25A22 knockout reduced MDSC infiltration, we hypothesized that SLC25A22 is required for tumor-induced MDSC chemotaxis through CXCL1/3." (PMID 37542037, 2023). "Importantly, SLC25A22 knockout plus anti-PD1 exerted synergistic effects as compared to single treatment (P < 0.01), leading to tumor regression and reduction in tumor weight." (PMID 37542037, 2023). "COX6c, SLC25A22, and MT-CO2 – all of which are mitochondrial inner membrane proteins – were selected for validation and tested for their presence in tumour tissue, because they were relatively highly abundant in our samples, and less commonly identified in other EV proteomic studies." (PMID 31497264, 2019). "To examine the possible role of SLC25A22 in LUAD, we first analyzed the expression of SLC2522 protein and mRNA in LUAD tissue and adjacent normal tissue from two databases: The Cancer Genome Atlas (TCGA) and Clinical Proteomic Tumor Analysis Consortium (CPTAC)." (PMID 40298644, 2025). "Here, we reveal that SLC25A22, a mitochondrial glutamate carrier, is involved in maintaining an immune repressive microenvironment in KRAS-mutant CRC, and that targeting SLC25A22 could re-activate antitumor immunity and synergize with anti-PD1 to induce tumor regression." (PMID 37542037, 2023). "In both models, SB265610 suppressed MDSC infiltration in controls but not in SLC25A22 knockout tumors, and intratumoral MDSC correlated with tumor burden (P < 0.05)." (PMID 37542037, 2023).